RUNX2 (RUNX family transcription factor 2)
Diseases named in the same sentence as RUNX2 in open-access papers (continued):
Sharing a sentence is not in itself a finding about the gene and the disease.
tumor (continued). "While RUNX2 expression is increased in tissues with CC, miR-218-5p expression is decreased; however, the RUNX2 level does not increase with the tumor stage, while miR-218-5p expression decreases." (PMID 35805994, 2022). "RUNX1 is a member of the RUNX family of transcription factors (RUNX1, RUNX2 and RUNX3), and is known to influence the malignancy of many neoplasms, including leukaemia, and to act as an oncogene or tumour suppressor gene with diverse functions depending on the tumour." (PMID 36085167, 2022). "We then evaluated the levels of tumor proteins from each group by immunohistochemical analysis, finding decreased levels of TAZ, C-MYC, RUNX2, N-cadherin, and CYR61 in ML323-treated tumors relative to those in controls, with these results confirmed by western blot analysis as well." (PMID 35637948, 2022). "In addition, we found that the expression of osteoblast-related genes RUNX2 and RANKL was reduced in tumor cells after DMAB treatment." (PMID 36172351, 2022). "Through the HPA database, we found that three genes, namely ABCC9, AHNAK, and DIP2C, had low expression in patients with tumours, and eight other genes—PLOD1, SLC3A2, RUNX2, RAD9A, CHMP4C, DARS2, CLIC3, and POU5F1—were highly expressed in patients with tumours." (PMID 36685927, 2022). "Additionally, the levels of tumor-promoting genes (Lrp5, MMP9, Runx2, and Snail) were increased by TGFβ and CXCL5, while they were reduced by TPM4, ANXA6, and Trail." (PMID 34230453, 2021). "CD44 and RUNX2, as well as the EMT process, play a critical role in tumor metastasis." (PMID 34769497, 2021). "In addition, it was shown in HCC cells that ZNF521, acting as a co-transcriptional repressor, binding Runx2 and inhibiting its transcriptional activity involving PI3K/AKT signaling, blocks the tumor progression." (PMID 34445164, 2021). "In our tumor series, miR-20a-5p expression was correlated to TTBM, inversely correlated to the expression of the BM protective gene OPG and correlated to the expression of several genes involved in BM (RUNX2, TCF7 and IL11)." (PMID 33800656, 2021). "The western blot results showed that in EO771 cells, A5 CM downregulated tumor-promoting genes such as Sclerostin, Lrp5, β-catenin, MMP9, Runx2, TGFβ, and Snail and elevated the level of an apoptosis marker, cleaved caspase 3, more substantially than did Y4 CM." (PMID 34230453, 2021). "In evaluating the Lrp5-mediated and Lrp5-non-mediated mechanisms of loading-driven tumor suppression, we examined the expression of oncogenic genes such as Runx2, Snail, and TGFβ in the context of Lrp5 overexpression and silencing." (PMID 33450808, 2021). "Tumor HMGB1 and TLR4/RAGE receptors promote cell proliferation, survival, migration, epithelial-to-mesenchymal transition, and apoptosis resistance involving interaction with β-catenin, Runx2, YAP1, and TGF-β1/Smad." (PMID 33669632, 2021). "In addition, we examined protein levels of several LPS141 tumor-promoting genes (i.e., RUNX1, c-MYC, FOSL2, RUNX2, and SNAI2) after ETC-168 treatment." (PMID 33564073, 2021). "We have previously shown that RUNX2, CD44s, and MMP9 are highly expressed in tumor tissue." (PMID 33062960, 2020). "Additionally, RUNX2 promotes the CRC EMT through activation of fibroblasts, i.e., the transition into myofibroblasts, which are known to facilitate tumor growth and invasiveness." (PMID 32139701, 2020). "In 7801 tumor tissues, ASPH also showed a positive correlation with RUNX2 as well as COL1A1." (PMID 33015050, 2020). "An observation of immediate therapeutic significance was the increased expression of hedgehog (HH), RUNX family transcription factor 2 (RUNX2), fibroblast growth factor receptor (FGFR) and insulin-like growth factor (IGF) in whole tumours when compared to controls." (PMID 32655131, 2020).
tumor (continued). "Pharmacological studies have found that Atractylodis Rhizoma and its extracts and active ingredients have the ability to interfere with BMP signaling in endothelial cells, downregulate Runx2 activation, and inhibit MMP expression and VEGF secretion, thereby inhibiting tumor formation." (PMID 33193894, 2020). "A large number of oncogenes as target genes of miR-505 in tumor cells, including TGF-α, HMGB1, FZD4, IGF1R, WNT7B, MAP3K3, NRCAM, and RUNX2, have been recognized as direct target genes of miR-505." (PMID 33520999, 2020). "The cocultivation of the tumor cells with hepatocytes did not cause increased expression of OPN and RUNX2, whereas the addition of TGF-β1 induced overexpression of OPN and Runx2 in tumor cells but not in cocultured hepatocytes." (PMID 28770169, 2017). "Taken together, calcium, RUNX2, and PTHLH form a positive feedback loop that may increase protein expression of RUNX2/PTHLH axis and promote the in orthotopic tumor growth by an autocrine/paracrine PTHLH manner." (PMID 28120940, 2017). "Depletion of RUNX2 from MGC803 and XN0422 cells reduced tumor invasiveness (P < 0.01)." (PMID 27007162, 2016). "Furthermore, several studies suggested a functional cooperation of RUNX2 and the PI3K/AKT pathway as a driving force for tumor progression in different cancer types." (PMID 27102439, 2016). "In RUNX2 Tet.OFF cells, DECMA-1 increased tumorsphere size in low RUNX2 expressing cells, consistent with other findings that neutralizing antibodies targeting E-Cadherin stimulate MCF7 growth by inhibiting its tumor suppressor function." (PMID 26320173, 2015). "PCR analysis of control (SAH) and experimental (SAM) treated LM-7 cells showed a marked inhibition in the expression of tumor-promoting genes (MMP-2, MMP-9, VEGF, PAI-1, and uPA) and genes (uPA, TFG-β, and RUNX2) which are known to promote the development and progression of skeletal metastasis." (PMID 25619880, 2015). "We therefore applied a cut-off of weighted histoscore of 25 in the training set (TMA-1) and carried out Kaplan-Meier analysis, comparing tumours with high RUNX2 (histoscore >25) and negative/low RUNX2 (histoscore <25)." (PMID 24626992, 2014). "To test whether progression RIS targets were also selected by their high transcription rates in premalignant cells, we compared the transcriptomes of Runx2/MYC and control thymus at 10 days of age, several weeks before clonal tumours emerge." (PMID 24586197, 2014). "The results showed that AdLMP-1 increased the expression of both Runx2 and BMP-2 in OS cells, which suggested that the osteogenetic roles of Runx2 and BMP-2 may be involved in LMP-1-mediated tumor suppression." (PMID 24762763, 2014). "The median expression levels of RUNX2 and miR-10b in tumor tissue normalized using adjacent non-tumor tissue were significantly higher in relapsed patients than in relapse-free patients." (PMID 25266482, 2014). "Positive RUNX2 staining was detected in the epithelium of a proportion of tumours (67/416) and scored as negative in the remaining patients." (PMID 24626992, 2014). "Thus, our data support the concept of oncogenic role of RUNX2 in EOC, and support previous findings for its rather universal functions in tumorigenesis, including tumor invasion and metastasis." (PMID 24124450, 2013). "As for RUNX2, none of the tumour samples showed gain of DLX5, but all showed increased expression at similar levels as the cell lines showing over-expression." (PMID 23144859, 2012). "None of the tumour samples showed gain of RUNX2, in contrast to the cell lines, but all showed increased expression at similar levels as the cell lines showing over-expression." (PMID 23144859, 2012).
tumor (continued). "In addition, Runx2 has the potential to regulate the transcription of extracellular matrix modulators such as SPARC and MMP1, thereby influencing the tumour microenvironment." (PMID 17876328, 2007). "The tumour microenvironment, such as matrix stiffness and composition, activate mechanotransduction pathways (e.g., integrin–FAK, YAP/TAZ) that promote EMT and metabolic reprogramming, processes intersecting with RUNX2–sterol regulatory element-binding protein 1 (SREBP1) signaling." (PMID 41511334, 2025). "Moreover, RUNX2 may support this process by stabilizing and preventing HIF-1α production in tumour cells." (PMID 40806771, 2025). "The target genes of Runx2—vascular endothelial growth factor (VEGF), angiopoietin-1 (Ang-1), BSP, OPN, and matrix metalloproteinases (MMPs)—promote the differentiation, migration, and invasion of endothelial cells during angiogenesis, which is crucial for tumor growth and metastasis." (PMID 39595568, 2024). "Although the cytomorphological aspects of some of these GC are similar to those of atypical megakaryocytes and megakaryoblasts, the GC we describe express tumor markers: telomerase, syncytin and Runx2, and macrophage markers which are not expressed by cells of the megakaryocyte series." (PMID 37316755, 2023). "Here, a genetically inactivated RUNX2, which lacked the transactivation domain, eliminated the original potential of the tumor cells to regulate osteogenic differentiation in bone marrow stromal cells in vitro and their ability to induce osteolytic disease in vivo." (PMID 36831308, 2023). "In addition, RUNX2 overexpression led to the upregulation of MMP1, which might degrade the extracellular matrix in the tumor microenvironment." (PMID 37108164, 2023). "SPP1 was not activated by Fam50a or E-cadherin in Runx2-expressing tumor cells." (PMID 37150786, 2023). "In this sense, inhibition of the AP‐1, SMAD3 and RUNX1/RUNX2 pathways, in combination or not with the chemotherapeutic agent temozolomide, led to the subtype‐specific impairment of tumour growth, particularly in the context of the aggressive, mesenchymal‐like subtype." (PMID 37357610, 2023). "Eight genes (SLC3A2, DARS2, DIP2C, PLOD1, RUNX2, ABCC9, AHNAK, and CLIC3) may be involved in the malignant transformation of tumours, and three genes (CHMP4C, POU5F1, and RAD9A) may have a protective effect in patients with tumours." (PMID 36685927, 2022). "Besides, the expression levels of RUNX2 and MMP1 in tumor sections from both groups of xenograft tumor were detected by immunohistochemical staining, which showed that they were obviously lower in tumors of the shRUNX2 group compared with those of the NC group." (PMID 36483054, 2022). "Conversely, knockdown of endogenous Runx2 or stable expression of functionally deficient mutant versions of Runx2 restored organized acini structures in metastatic MDA-MB-231 in 3D culture and failed to promote tumor growth in vivo." (PMID 35205770, 2022). "In the same cell line, the highly expressed runt-related transcription factor 2 (RUNX2) forms a complex with the overexpressed CD44, thereby activating many metastasis-related genes, including MMP-9, and consequently contributes to tumour sphere formation and migration." (PMID 34944493, 2021). "Moreover, RUNX2 downstream AKT/β-catenin/Survivin (also known as BIRC5) signaling pathway was suppressed, leading to deregulation of bone formation-related TCF and LEF transcription factors and consequently tumor suppression." (PMID 33673480, 2021). "According to Kim and his colleagues, connective tissue growth factor (CTGF) may regulate P300 acetyl transferase meditated acetylation to increase RUNX2 protein stability and meanwhile can promote RUNX2 recruitment to the RANKL promoter, resulting in increased RANKL production from the tumor cells." (PMID 34326880, 2021).
tumor (continued). "In addition to the recombinant Eno1 proteins, the partial silencing of CD44 in EO771 tumor cells reduced the inhibitory effect of recombinant Hsp90ab1 proteins on MTT-based viability, and partially suppressed the Hsp90ab1-driven downregulation of Lrp5, Runx2, and TGFβ in EO771 tumor cells." (PMID 34830748, 2021). "Importantly, the partial silencing of CD44 in EO771 tumor cells reduced the inhibitory effect of recombinant Eno1 proteins on the MTT-based viability, and partially suppressed the Eno1-driven downregulation of Lrp5, Runx2, and TGFβ in EO771 tumor cells." (PMID 34830748, 2021). "Furthermore, many (13/22) of the RUNX2-high tumours were negative for ER, PR and HER2 (the so-called triple-negative subtype)." (PMID 24626992, 2014). "Disrupting interactions between Runx2 and EWS-Fli1 may promote differentiation of the tumor cells." (PMID 29147265, 2011). "Furthermore, the absence of ERα in primary tumors was associated with lung- and brain- but not with bone metastasis, and tumor biopsies from bone metastatic sites displayed the unusual combination of high Runx2/SNAI2 and high ERα expression." (PMID 22151997, 2011). "However, recent studies demonstrate that HER2+ tumor cells can acquire an osteoblastic phenotype, actively producing hydroxyapatite crystals through activation of epithelial-mesenchymal transition (EMT) and the expression of genes such as BMP-2, RUNX2, and osteopontin." (PMID 40725750, 2025). "It will be interesting to investigate whether some tumor suppressive functions of SMURF2 could be related to its negative effects on RUNX2 and whether AKT-mediated degradation of SMURF2 can occur in tumors, explaining the high levels of RUNX2 in certain types of cancer." (PMID 26204939, 2015). "Also, the expression of ALP, OPG, OCN, Runx2 and Collagen I of PP5 group were significantly higher than Control group, indicated that PP5 scaffold could promote bone growth and might be a suitable option for bone tissue engineering; however, it cannot inhibit tumor metastasis." (PMID 37663244, 2023). "We found that the knockdown of RUNX2 but not TEAD or P73 upregulated the expression of MAFG and stemness genes in stiff tumor cells." (PMID 37614365, 2023). "The expression of RUNX2 and SCD1 protein was significantly correlated with Fuhrman grade but failed to be remarkably related to age, gender, tumor stage, and tumor size." (PMID 36200301, 2023). "Taken together, the result supported the anti-tumor action of extracellular Hsp90ab1, and not Hsp90aa1, in regulating Lrp5, Runx2, TGFβ, and IL27 in tumor cells." (PMID 34830748, 2021). "By contrast, MSCs did not present the innate anti-tumor actions but the overexpression of Lrp5 converted them into anti-tumor agents by reducing the MTT-based viability and downregulating MMP9, Runx2, and Snail, as well as N-cadherin in EO771 cells." (PMID 33802279, 2021). "In an in vitro cell model or in vivo tumor tissues, dipyridamole treatment resulted in a decline in the levels of HMGB1, RAGE, β-catenin, Runx2, YAP1, phosphorylated Smad2/3, and cyclin D1, but not TLR2 and TLR4." (PMID 33669632, 2021). "High RUNX2 expression was observed in HCC tissues, with clear nuclear localization in the tumor hepatocytes but not in NL hepatocytes." (PMID 27336713, 2016). "Interestingly, PTHLH only fully rescued the tumor growth abilities in Cal-27 cells, but not in SAS cells, after Runx2 knockdown." (PMID 28120940, 2017). "Notably, expression of RUNX2 is specifically observed in cell lines of the ‘basal-like’ subtype (ER/PR/HER2-negative) and not in those derived from ‘luminal-like’ tumours." (PMID 24626992, 2014).
cancer (268 papers, 2007 to 2026). A tumor composed of atypical neoplastic, often pleomorphic cells that invade other tissues. "We observed that SREBP1 silencing impaired cell proliferation and caused a strong reduction in cancer cell migration and invasion, recapitulating the RUNX2 KD phenotype and confirming its importance in TC aggressiveness." (PMID 41174748, 2025). "Studies have implicated RUNX2 in migration of solid tumor cells where RUNX2 overexpression induces cancer cell invasion and metastasis." (PMID 41511334, 2025). "Overall, evidence predominantly supports RUNX2's role in enhancing stem cell-like characteristics in a range of cancers, which is often linked to worse patient outcomes." (PMID 38430423, 2024). "l‐Carnitine, a marker of cancer cachexia, can alleviate fibrosis in liver and kidney models; however, its role in cancer cachexia‐associated fibrosis and the involvement of Runx2 in the process remain unexplored." (PMID 39091264, 2024). "Of notice, ectopic RUNX2 expression has also been linked to genomic instability and drug resistance in cancer." (PMID 39435287, 2024). "For example, the genetic variants of the RUNX2 gene in cancer patients were recently reviewed by Lin T-C." (PMID 39684309, 2024). "RUNX2 is associated with many cancers and has been shown to be a risk factor for invasion and metastasis in different carcinomas." (PMID 37509363, 2023). "Studies have suggested that RUNX2 is associated with malignancy progression, functioning in the invasive and migrating behaviour of a number of carcinomas, including cancers in prostate, bladder and mantle cell lymphoma." (PMID 37525479, 2023). "Atherosclerosis, skeletal dysplasia (including cleidocranial dysplasia), and cancer have all been linked to abnormal RUNX2 expression or activity." (PMID 37370857, 2023). "Genetic variants of the RUNX2 gene in patients with cancer have been comprehensively addressed reported." (PMID 37108164, 2023). "Due to the complex regulatory mechanisms of RUNX2, the specific mechanism underlying its involvement in the occurrence, development, and prognosis of malignant tumors is not fully understood." (PMID 37754231, 2023). "Runt-related transcription factor 2 (RUNX2) has a key role associated with the pathogenesis of some cancers and a downstream gene of the STAT3 pathway." (PMID 36547079, 2022). "Accumulating evidences have confirmed the oncogenic role of RUNX2 in several cancers, and it has also been associated with the prognosis of patients with recurrence and metastasis." (PMID 33071648, 2020). "RUNX2 is a direct target of miR-1305, and its up-regulation is associated with a variety of cancer tissues." (PMID 31487369, 2020). "In the recent years, several researches have indicated that changes in the RUNX2 expression are closely associated with the occurrence and development of malignant tumors." (PMID 33071648, 2020). "While RUNX2 isoform 2 expression is restricted to bone lineage, isoform 1, transcribed from the proximal P2 promoter, is the only RUNX2 variant expressed in cancer cells." (PMID 31395086, 2019). "RUNX2 has been implicated as a primary candidate to regulate adhesion and migration of cancer cells." (PMID 31331331, 2019). "Of note, overexpression of RUNX2 has been shown to cause a poor response to chemotherapy of certain cancer cells." (PMID 29558908, 2018). "Runx-2 was first demonstrated to be a transcription factor that plays a remarkable role in diverse biological processes of chondrocytes and osteoblasts, but recently, Runx-2 has been reported to be associated with the progression of certain human cancers." (PMID 30105080, 2018). "Runt-related transcription factor 2 (RUNX2) is a regulator of embryogenesis and development, but has also been implicated in the progression of certain human cancer." (PMID 27007162, 2016). "The transcriptional activity of RUNX2 has been linked to the migration and invasion in different cancer types." (PMID 26388610, 2015).